ACHE (acetylcholinesterase (Yt blood group))
Diseases named in the same sentence as ACHE in open-access papers (continued):
Sharing a sentence is not in itself a finding about the gene and the disease.
Alzheimer disease (continued). "Tacrine (THA), the first clinically effective acetylcholinesterase (AChE) inhibitor and the first approved drug for the treatment of Alzheimer’s disease (AD), was withdrawn from the market due to its side effects, particularly its hepatotoxicity." (PMID 28788095, 2017). "The regulation of memory function depends upon the levels of neurotransmitter such as acetylcholine (ACh), choline acetyltransferase (ChAT) and acetyl cholinesterase (AChE) which are critical components of Alzheimer’s disease." (PMID 28078250, 2016). "Previous studies have demonstrated that berberine possesses multiple activities in Alzheimer's disease therapy, including antioxidant activity, AChE and BChE inhibitory activity, MAO inhibitory activity, and reducing Aβ level and lowering cholesterol." (PMID 27769241, 2016). "Amaryllidaceae alkaloids are an important resource for new drug discovery, among them, galanthamine, a well-known acetylcholinesterase (AChE) inhibitor, is a first-line treatment of Alzheimer’s disease." (PMID 27658482, 2016). "Inhibition of acetylcholinesterase (AChE) using small molecules is still one of the most successful therapeutic strategies in the treatment of Alzheimer’s disease (AD)." (PMID 27441112, 2016). "Detection of marker proteins for cardiovascular disease, cancer, Alzheimer’s disease (AChE) or virus infections are the prospective aims in the generation of MIPs." (PMID 27438862, 2016). "It was shown that Teucrium polium L (due to its proven AChE inhibitory capacity and antioxidant properties) is a new promising candidate and alternative medicine for treatment or prevention of Alzheimer’s disease and related disorders." (PMID 27776515, 2016). "Inhibition of acetylcholinesterase (AChE) is a common treatment for early stages of the most general form of dementia, Alzheimer’s Disease (AD)." (PMID 27589716, 2016). "The enhanced activity of AChE and BChE is detrimental to patients suffering from Alzheimer's disease." (PMID 27486373, 2015). "AChE inhibitors are the most effective approach to treat the cognitive symptoms of Alzheimer disease and other possible therapeutic applications in the treatment of Parkinson.s disease, senile dementia, and ataxia, among others." (PMID 25889712, 2015). "Recently, some AChE inhibitors like tacrine and rivastigmine were used in the treatment of Alzheimer’s disease." (PMID 26400617, 2015). "Like other AChE inhibitors, HupA has been most commonly evaluated in patients with Alzheimer’s disease with specific focus on its ability to improve cognition." (PMID 26364275, 2015). "The present study of adaptive processes in the central cholinergic system was motivated by the use of AChE inhibitors in human disease, primarily for the treatment of dementias such as Alzheimer ́s disease (AD)." (PMID 26506622, 2015). "Several AChE inhibitors named as “cognitive enhancers “are being investigated for the symptomatic treatment of Alzheimer’s disease but few have been approved by the Food and Drug Administration in the United States." (PMID 24401532, 2014). "Compared to other drugs for Alzheimer disease, donepezil works via a simple pathway based on AChE inhibition." (PMID 24893223, 2014). "Acetylcholinesterase (AChE) inhibitors are widely used for the symptomatic treatment of Alzheimer’s disease and other dementias." (PMID 24893223, 2014). "ACHE inhibitors are investigated largely as a treatment option for Alzheimer’s disease and an interaction was found between ache and presenilin-1 levels." (PMID 24548546, 2014). "AChE inhibitors such as tacrine, donepezil, and rivastigmine are commonly used synthetic drugs for the treatment of Alzheimer's disease; however, these drugs are limited in use due to their adverse side effects." (PMID 25506036, 2014). "Laser acupuncture at HT7 is demonstrated to suppress AChE in hippocampus together with the improved memory impairment in animal model of Alzheimer's disease." (PMID 25161693, 2014).
Alzheimer disease (continued). "As referred above, AChE plays an important role in Alzheimer’s disease, because its “reversible” inhibition has a great therapeutic potential." (PMID 25153865, 2014). "Inhibitors of AChE and BChE enzymes are the most valuable approaches to treat neurological diseases including Alzheimer's disease (AD) and possible beneficial applications in the treatment of Parkinson's disease, ataxia and dementia." (PMID 24884823, 2014). "Reversible AChE inhibitors are prescribed for medical conditions of reduced acetylcholine function including myasthenia gravis and Alzheimer’s disease." (PMID 24904300, 2014). "Acetylcholinesterase (AChE) inhibitors are used in the treatment of various neuromuscular disorders, and are considered as strong therapeutic agents for the treatment of Alzheimer’s disease (AD)." (PMID 24918454, 2014). "Compared to drugs for Alzheimer disease penetrating through the blood-brain barrier, drugs for myasthenia gravis, such as pyridostigmine and neostigmine, inhibit AChE in peripheral nerves." (PMID 23698772, 2013). "Huperzine and its derivative, ZT-1, donepezil, galantamine and rivastigmine can be mentioned as drugs for Alzheimer disease inhibiting AChE." (PMID 23698772, 2013). "As acetylcholinesterase (AChE) inhibitors are an important therapeutic strategy in Alzheimer’s disease, efforts are being made in search of new molecules with anti-AChE activity." (PMID 24381530, 2013). "Donepezil, an Acetyl Cholinesterase inhibitor (AChE), is commonly prescribed to patients with Alzheimer's disease (AD) to enhance cholinergic neurotransmission." (PMID 24062965, 2013). "Little is known of vitamin D concentration in cerebrospinal fluid (CSF) in Alzheimer ́s disease (AD) and its relation with CSF acetylcholinesterase (AChE) activity, a marker of cholinergic function." (PMID 24312390, 2013). "For instance, the hydroalcoholic extract of the plant was tested in vitro against acetylcholinesterase (AChE), the key enzyme taking a critical role in the pathogenesis of Alzheimers disease (AD)." (PMID 22666298, 2012). "Conversely, AChE is a well-studied enzyme and abundant literature details the development of effective AChE inhibitors, some of which are used currently as insecticides or others as clinical drugs for treating Alzheimer’s disease." (PMID 22280344, 2012). "AChE inhibitors are among the approved pharmacological treatments of Alzheimer's disease, myasthenia gravis, and glaucoma." (PMID 22438795, 2012). "An important approach to treat Alzheimer’s disease involves the inhibition of the enzyme acetylcholinesterase (AChE)." (PMID 23149565, 2012). "Acetylcholinesterase (AChE) has proven to be the most viable therapeutic target for symptomatic improvement in Alzheimer's disease (AD) because cholinergic deficit is a consistent and early finding in AD." (PMID 22216416, 2012). "Hologram QSAR models were developed for a series of 36 inhibitors (29 training set and seven test set compounds) of acetyl/butyrylcholinesterase (AChE/BChE) enzymes, an attractive molecular target for Alzheimer’s disease (AD) treatment." (PMID 22878227, 2012). "Donepezil, which is an antagonist of AChE, is a clinically approved medication used to treat Alzheimer's disease patients." (PMID 22114680, 2011). "The carbamate moiety has been, and still is, a key functional group in medicinal chemistry programs to develop drugs targeting AChE, for example the drugs pyridostigmine 4 (myasthenia gravis) and rivastigmine 5 (Alzheimer's disease)." (PMID 22140425, 2011). "In drug discovery programs, AChE inhibitors are of great interest for treatment of cholinergic deficiencies in the PNS (e.g. myasthenia gravis) and CNS (e.g. Alzheimer's disease)." (PMID 22140425, 2011). "Inhibitors of AChE, such as galanthamine, are used frequently in the pharmacotherapy of Alzheimer Disease: AChE is, indeed, dramatically down-regulated in the brains of patients suffering from this disease." (PMID 22254099, 2011).
Alzheimer disease (continued). "Rivastigmine hydrogen tartrate, i.e. (−)S-N-ethyl-3-[(1-dimethyl-amino)ethyl]-N-methylphenyl- carbamate hydrogen tartrate, is a carbamate inhibitor of acetylcholinesterase (AChE) used in the treatment of mild to moderate Alzheimer’s disease in adults." (PMID 24363716, 2010). "This prompted us to continued synthesizing benzofuran derivatives through the rearrangement of coumarins to expand our efforts on developing novel AChE inhibitors for treating Alzheimer’s disease (AD)." (PMID 21116228, 2010). "AChE is a well-studied enzyme and there is extensive literature on developing effective AChE inhibitors several of which are used currently as insecticides or even as clinical drugs for treating the Alzheimer's disease." (PMID 19714254, 2009). "Under pathological conditions, such as stroke, head trauma and Alzheimer's disease, neuronal choline, AChE, and α7-nAChR levels increase significantly." (PMID 19287501, 2009). "AChE586-599 was chosen due to its fibrilization tractability and AChE involvement in Alzheimer's disease." (PMID 18350169, 2008). "This study reports the design and synthesis of a novel series of cinnamic acid-based analogs bearing an N-benzyl pyridinium moiety against Alzheimer's disease (AD), aiming at dual inhibition of acetylcholinesterase (AChE) and butyrylcholinesterase (BChE), alongside neuroprotective effects." (PMID 41704453, 2026). "The cholinergic pathway involved in cognitive deficit and Alzheimer’s disease (AD) is the target of activity of the AChE enzyme that plays a role in breaking down or hydrolyzing acetylcholine, raising acetylcholine levels in the brain and resulting in improved cognitive functions in AD." (PMID 40231970, 2025). "An example is the identification of two lactones as potential inhibitors of acetylcholinesterase (AChE), an important target of research in Alzheimer’s disease, found based on 7032 molecules with IC50 and another 8593 secondary metabolites through classification models." (PMID 40076924, 2025). "Furthermore, given the relevance of AChE in neurotoxicity evaluation, diagnosis of neurological disorders such as Alzheimer's disease, and environmental toxicity monitoring, this method has diverse potential applications." (PMID 40933087, 2025). "The p(TA-co-LYS) nanogels have also shown high potential use as therapeutic agents to be used in the treatment of neurodegenerative diseases such as Alzheimer’s disease, due to their antioxidant and Fe(II) ion chelating capacity, as well as their AChE enzyme-inhibiting abilities." (PMID 40284497, 2025). "Additionally, Huperzine B—a natural alkaloid derived from Huperzia species—exhibits potent acetylcholinesterase (AChE) inhibitory activity, demonstrating therapeutic potential for Alzheimer’s disease (Knölker, 2013)." (PMID 41036228, 2025). "Additionally, compounds such as β–carotene have been investigated for their neuroprotective properties and their ability to modulate AChE activity, potentially offering new avenues for Alzheimer’s disease treatment." (PMID 40243991, 2025). "Overall, these findings expand our knowledge of secondary metabolites in native Luzuriaga species and validate their bioactivity, especially their potential as a supplement in aid of Alzheimer’s disease (inhibition of the AChE enzyme), laying the groundwork for future studies." (PMID 40872178, 2025). "Notably, SM demonstrated considerable inhibitory activity against AChE, highlighting its potential for cholinergic enhancement, which is a crucial focus in the treatment of Alzheimer’s disease." (PMID 40729025, 2025). "In addition, acetylcholinesterase (AChE) and butyrylcholinesterase (BChE) are other critical enzymes in health care, and their inhibitors are used in the clinical management of Alzheimer’s disease." (PMID 40649366, 2025).
Alzheimer disease (continued). "This study provides a preliminary foundation based on the in vitro inhibition of AChE, a key biomarker in the treatment of Alzheimer’s disease, and the AChE-inhibitory activity and moderate antioxidant properties of the EOs open new possibilities for future research." (PMID 40649231, 2025). "A novel series of 4‐(diethylamino)salicylaldehyde‐based thiosemicarbazone derivatives 5(a–u) were synthesized and screened for their potential against Alzheimer's disease, by testing for their inhibitory effects against cholinesterases (AChE and BChE) and monoaminoxidase A (MAO‐A) and B (MAO‐A)." (PMID 40685770, 2025). "While clinically approved AChE inhibitors such as donepezil, rivastigmine, and galantamine are used in the symptomatic treatment of Alzheimer’s disease and related dementias, little is known about the modulatory effects of common dietary compounds on AChE activity." (PMID 41373466, 2025). "For instance, AChE is a central enzyme involved in the hydrolysis of acetylcholine, and the inhibition of AChE has been the most widely embraced method of treatment for Alzheimer’s disease." (PMID 40649369, 2025). "Molecular docking serves as a powerful computational method in the search for effective AChE inhibitors, facilitating the identification and optimization of compounds that may lead to new therapeutic options for Alzheimer’s disease." (PMID 40243991, 2025). "Furthermore, HM is considered a potential candidate for the treatment of Alzheimer's disease as it inhibits acetylcholinesterase (AChE) and butyrylcholinesterase (BChE) activity." (PMID 40496271, 2025). "However, the specific role of peanut shells as AChE inhibitors, a mechanism critical for Alzheimer's disease therapy, remains underexplored." (PMID 40548191, 2025). "Finally, AChEs as an enzyme class are known druggable targets; AChE inhibitors have been used in the treatment of various human diseases, such as myasthenia gravis, Alzheimer’s disease, postoperative ileus, bladder distention and glaucoma." (PMID 40076600, 2025). "AChE inhibition is a validated therapeutic strategy, as reducing the degradation of acetylcholine enhances cholinergic neurotransmission, a key aspect in mitigating the symptoms of Alzheimer’s disease." (PMID 40332446, 2025). "This hypothesis underscores the importance of AChE inhibitors in restoring cholinergic function and improving cognitive outcomes in Alzheimer’s disease patients." (PMID 40243991, 2025). "The results show ligand-assisted stability and increased antibacterial and anti-AChE activities show that these NPs could be consider in treating antimicrobial resistance and Alzheimer’s disease." (PMID 40819011, 2025). "The cholinergic hypothesis posits that the cognitive decline in Alzheimer’s disease is primarily due to reduced acetylcholine synthesis and increased AChE activity, leading to diminished cholinergic signaling." (PMID 40243991, 2025). "Notably, 5,7,4′-trimethoxyflavone and 5,7-dimethoxyflavone have demonstrated potent inhibitory effects on acetylcholinesterase (AChE) and butyrylcholinesterase (BChE), suggesting their therapeutic potential in treating Alzheimer’s disease." (PMID 41375950, 2025). "Another significant property is its ability to inhibit acetylcholinesterase (AChE), which may be relevant in the treatment of neurodegenerative diseases, such as Alzheimer’s disease." (PMID 40286078, 2025). "The inhibition of AChE is a crucial therapeutic target in the management of neurodegenerative disorders, such as Alzheimer’s disease, due to the fundamental role of this enzyme in regulating cholinergic neurotransmission by hydrolyzing acetylcholine at neuronal synapses." (PMID 41515358, 2025). "Alzheimer’s disease is characterized by high levels of BChE activity in the later stages as a compensatory mechanism for downregulating the activity and function of acetylcholinesterase (AChE)." (PMID 41304964, 2025).
Alzheimer disease (continued). "The inhibition of AChE remains a vital strategy in the management of Alzheimer’s disease." (PMID 40243991, 2025). "AChE is a crucial enzyme that hydrolyzes acetylcholine into choline and acetic acid, and its inhibition is considered a cornerstone in the symptomatic treatment of Alzheimer’s disease." (PMID 40243991, 2025). "The main drugs currently approved by the FDA for the treatment of Alzheimer’s disease, AchE, and NMDAR inhibitors, are administered orally, so high doses are required for the therapeutic fraction to reach the brain and overcome oral absorption barriers, hepatic metabolism, and finally cross the BBB." (PMID 39861773, 2025). "The research and design of new inhibitors for the treatment of diseases such as Alzheimer's disease and glaucoma through inhibition of cholinesterases (ChEs; acetylcholinesterase, AChE and butyrylcholinesterase, BChE) and carbonic anhydrase enzymes are among the important targets." (PMID 40129107, 2025). "Furthermore, studies have shown that bioactive compounds in F. fomentarius can reduce AChE activity, suggesting its potential as a neuroprotective agent in conditions such as Alzheimer’s disease." (PMID 40572099, 2025). "Moreover, Diels−Alder-type adducts have been characterized as multitargeted agents for Alzheimer’s disease; mulberrofuran G and albanol B showed strong AChE- and BChE-inhibitory activities." (PMID 38257228, 2024). "The extracts also showed inhibitory activity on AChE and BChE enzymes at levels comparable with inhibitors obtained from other natural sources, exhibiting potential for use in treatments aiming to fight and/or protect against Alzheimer’s disease." (PMID 38254569, 2024). "Acetylcholinesterase (AChE) is one of the main drug targets for treating Alzheimer’s disease." (PMID 39065681, 2024). "AChE inhibitors are currently the most prescribed drug class for the treatment of Alzheimer’s disease (AD) based on the treatment relevant to the cholinergic hypothesis." (PMID 39199238, 2024). "STZ or Aβ1–42 treatment in neuronal N2A cells and cortex & hippocampal regions of rat brain exhibited the significantly augmented level of Pirh2 along with Alzheimer’s disease markers like upregulated p-Tau and β-amyloid, increased AChE activity and neuronal apoptosis." (PMID 38740775, 2024). "With respect to human AChE inhibitory activity, there is increasing interest in the application of AChE in preventing and treating Alzheimer disease and, more recently, in the application of AChE from arthropods due to the resistance phenomena among diverse tick infestations, such as R. microplus." (PMID 38695451, 2024). "We considered both acetylcholinesterase (AChE) and butyrylcholinesterase (BChE) due to their physiological roles as therapeutic targets involved in the symptoms of Alzheimer’s disease, in the treatment of which the currently available drugs are AChE inhibitors." (PMID 38667790, 2024). "Some of the plant extracts obtained in our study, especially the ethyl acetate and the butanolic ones, exhibited potent antioxidant, AChE, and BChE inhibitory activities, and anti-neurotoxic potential, properties that may be useful against Alzheimer’s disease." (PMID 39684612, 2024). "The inhibition of AChE and BChE by taxifolin is likely due to its ability to bind to their active sites, which could have therapeutic implications for the treatment of Alzheimer’s disease and other neurodegenerative disorders." (PMID 38338420, 2024). "Moreover, lupeol significantly reduced AChE activity in LPS-induced neuroinflammation model of Alzheimer’s disease like pathologies." (PMID 39050141, 2024). "For instance, acetylcholinesterase (AChE) inhibitors increase cholinergic levels in the brain to treat Alzheimer’s disease (AD), by enhancing the cholinergic levels in the brain, while monoamine oxidase (MAO) inhibitors reduce oxidative damage and have the potential for treating AD." (PMID 38790018, 2024).